CXCL12 (C-X-C motif chemokine ligand 12)
Diseases named in the same sentence as CXCL12 in open-access papers (continued):
Sharing a sentence is not in itself a finding about the gene and the disease.
tumor (continued). "Nevertheless, some tumour cells, possibly equipped with unidentified particularly invasive characteristics, do escape the primary tumour and may then use the CXCR4/CXCL12 axis to specifically migrate toward CXCL12 producing organs such as the liver." (PMID 17925864, 2007). "Although in this study we focused on the effect of VHL inactivation on CXCL12/CXCR4-mediated organ-specific metastases, it is possible that other hypoxia-inducible genes under the control of HIF-1α/VHL pathway may also play a role in tumor metastasis." (PMID 17083723, 2006). "This is consistent with our previous study using a NSCLC-bearing mouse model, and indicates that the function of CXCL12 may not be as important in promoting angiogenesis, proliferation, and cell survival in the local tumor microenvironment of RCC." (PMID 17083723, 2006). "The CXCL12/CXCR4 axis may help maintain this dormant state through activation of downstream signalling pathways (e.g., PI3K/AKT, ERK1/2) and interactions with the tumour microenvironment, including stromal and immune cells, which support cell survival without promoting proliferation." (PMID 41002447, 2025). "Therefore, the published articles, in conjunction with our results, indicate that tumor cell-derived exosomes transmit HIF2A mRNA to peritumoral fibroblasts, which is then translated into HIF-2α protein, forms a heterodimer with HIF-1β, enters the cellular nucleus, and induces CXCL12 expression." (PMID 40756343, 2025). "Critically, VTN expression correlated with key immunomodulators: positive associations with CXCL12 (a chemokine promoting T-cell recruitment) and negative trends with PD-L1/CTLA4 (immune checkpoint mediators) suggest that VTN may remodel the tumor immune microenvironment." (PMID 40433359, 2025). "The increased expression of CXCL12 and CSF1 in senescent CRC tumor cells establishes a cytokine barrier that suppresses immune infiltration by tumor-associated T cells, thereby protecting non-senescent tumor cells from immune attack and promoting resistance to CRC." (PMID 40896432, 2025). "In addition, Insulin-like growth factor-1/2(IGF1/2), chemokine (C-X-C motif) ligand 12(CXCL12), and beta-hydroxybutyrate produced by CAFs can induce autophagy of cancer cells after RT, and promote recovery of irradiated cancer cells and tumor regeneration after RT." (PMID 37600785, 2023). "Notably, neither BoxA nor CXCL12 induce tumor cell apoptosis, and are not toxic to mice." (PMID 35565443, 2022). "Although it has previously been reported that neutrophils can secrete and chemoattract CD8+ Teffs via CXCL12, the tumor stroma could not be ruled out as the main source; this question was not addressed in the current study and would be important to address as part of a future investigation." (PMID 35552271, 2022). "In addition to CAF-derived soluble factors CXCL12, IL-6, and TGF-β, CAFs also inhibit antitumor cytotoxicity of CD8+ T cells through the acquisition of immune checkpoint molecules, such as programmed cell death ligand 1 (PD-L1), PD-L2, and Fas ligand in several tumor types." (PMID 33673405, 2021). "Moreover, CXCL10, CXCL12, and CCL7, which may promote tumor progression, were also highly induced." (PMID 34771453, 2021). "Besides the CXCR4/CXCL12 axis, other studies have implicated the CCL2/CCR2 axis in vitro and in animal models, although the experimental design used in these studies more specifically addressed tumor growth into bones rather than homing from distant sites." (PMID 33671469, 2021). "Despite the fact that CXCL12 can promote the detachment of cancer cells from the primary tumor and their entry into the bloodstream in response to a metastatic site-driven gradient, the role of this cytokine in controlling tumor progression and metastasis in primary ACC has not yet been assessed." (PMID 34834449, 2021).
tumor (continued). "Moreover, crosstalk regulation between the mTOR pathway and the CXCL12/CXCR4 axis suggests that mTORC1 silencing is sufficient to decrease CXCR4-mediated cancer cell migration, and inhibition of mTORC1 by rapamycin decreases primary tumor growth and CXCR4-mediated lymph node metastasis." (PMID 32498358, 2020). "In addition, stromal cell-derived factor (SDF-1) also known as C-X-C motif chemokine 12 (CXCL12), secreted by stromal fibroblasts binds its cognate receptor CXCR4 on epithelial cells to trigger several downstream pathways involved in cell proliferation, cancer cell invasion and tumor angiogenesis." (PMID 33227080, 2020). "Since both CXCL12 and CXCR4 are highly expressed in normal brain, where CXCL12-CXCR4 axis plays an important role in the CNS development, the involvement of this chemokine-receptor axis in glioblastoma may be considered as an example of tumor cells “hijacking” of physiological processes in CNS." (PMID 32456359, 2020). "Thus, tumor progression may be directed by reciprocal interaction between stromal cells and tumor cells, by chemotactic action of MCP-1/CCL2 and SDF-1/CXCL12 and probable, effect of MSC-derived exosome, to create an appropriate environment for tumor aggressiveness." (PMID 30413179, 2018). "Additional transwell experiments showed that effector B cells could directly kill tumor cells in cell-cell contact via the Fas/FasL and CXCR4/CXCL12 pathways as well as perforin, while without cell contact, perforin secreted by B cells led to tumor cell cytotoxicity." (PMID 27528023, 2016). "Collectively, these results indicate that effector B cells directly kill tumor cells in cell-cell contact via the Fas/FasL and CXCR4/CXCL12 pathways as well as perforin, while without cell contact, perforin secreted by B cells could also lead to tumor cell cytotoxicity." (PMID 27528023, 2016). "In addition, CXCL12-derived peptides, including the N-terminal amino acid sequence KPVSLSYR, were used as carriers for gene delivery to CXCR4 expressing cells demonstrating that this technique may be useful in gene therapy of tumor cells expressing CXCR4." (PMID 26062132, 2015). "However, it is unknown whether or not the elevation of Cxcl12 transcript found in marrow post-ablation is evidence of seeding premetastatic niches or the primary tumor site." (PMID 24270800, 2014). "This apparent paradox may be explained by the cellular expression of CXCL12 not providing a true reflection of its bioavailability, which depends principally on the presence in the tumor microenvironment of factors capable of disrupting CXCL12 from glycosaminoglycans." (PMID 21410972, 2011). "For instance, the CXCL12/CXCR4 axis is particularly pivotal in ESCC, where it not only promotes tumor growth but also facilitates lymphatic and vascular invasion." (PMID 40134607, 2025). "Through secretion of TGF−β and ARG2, CAFs induce M2 polarization of TAMs and expansion of Tregs, while CXCL12 produced by CAFs engages CXCR4 on T cells, forming a “chemokine barrier” that excludes CD8+ T cells from tumor nests." (PMID 40963620, 2025). "CXCL12 is a chemokine that is not CAF specific, but when present, it contributes to the formation of a tumor-supportive microenvironment through angiogenesis, immunomodulation, and extracellular matrix remodeling." (PMID 41450913, 2025). "In the current study, however, LEF1 depletion in 544 cells did not decrease mRNA expression of CXCL12 and TGF‐β, suggesting they are not involved in LEF1‐medicated tumor‐promoting effect of 544 cells." (PMID 39887653, 2025). "CXCL12 attracts cancer cells by binding to CXCR4, which is expressed on both hematopoietic and non-hematopoietic tumor cells." (PMID 39273290, 2024). "Analysis of stRNA-Seq data revealed a notable enhancement in the interaction intensity between CXCL12 and its predominant receptor CXCR4 on T cells in the IGF2hi tumor, unlike in the IGF2lo tumor." (PMID 39545420, 2024).
tumor (continued). "IFN-γ can induce the expression of more than 200 genes, including those involved in immune evasion by tumor cells, such as PD-L1, PD-L2, CTLA-4, CIITA, non-classical MHC class Ib antigens, IDO1, and CXCL12." (PMID 37444608, 2023). "We conclude that CXCL12 and CXCL11 commonly have pro-apoptotic effects on tumor cells, which in most cases are absent in the simultaneous presence of the chemokines." (PMID 36539774, 2022). "Although, evidence exists that CXCL12 and CXCL11 exert combined effects during tumor progression, putative interactions are currently not well characterized." (PMID 36539774, 2022). "The infiltration of CAR-T cells to the tumor site is significantly reduced when the chemokine receptor expressed by T cells is not compatible with chemokines secreted by tumor cells, as noted in the case of CXCL-1, CXCL-5, and CXCL-12." (PMID 35326556, 2022). "Interestingly, no downregulation of chemokines other than CXCL12 was found by Tranilast administration, though it is well known that CCL2 (MCP-1) is a major chemoattractant for recruiting monocytes, causing increased CCR2-expressing macrophage migration into the tumor site." (PMID 34997450, 2022). "The nanocages did not directly kill tumor cells but promoted T-cell infiltration by destroying the dense ECM in tumor tissue and inhibiting the secretion of CXCL12, thereby inhibiting tumor growth." (PMID 35566065, 2022). "We demonstrate that CXCL12 and CXCL11 interact to control migration, invasion, and survival of most, but not of all tumor cells." (PMID 36539774, 2022). "In contrast to single chemokines, CXCL12 and CXCL11 in combination more potently stimulated the migration of A549 and A767 cells, but not of the other tumor cells." (PMID 36539774, 2022). "Together, these findings establish that CXCL12 and CXCL11 synergistically control migration of some, but not of all tumor cells." (PMID 36539774, 2022). "We also noticed that more than 10 Mhc type II molecules and chemokines such as Cxcl12 were higher and lower in the absence of TNC, respectively, suggesting an impact of TNC on tumor immunity." (PMID 33988305, 2021). "Tumor-conditioned monocytes demonstrated an increase in in vitro migration in response to CCL5 and CXCL12 when compared to non-conditioned monocytes." (PMID 34975843, 2021). "Finally, by higher resolution tissue staining of TNC‐high tumors, we noticed a punctate CXCL12 signal in the stroma, importantly colocalizing with TNC and CD8 TIL, altogether suggesting that the described chemoretention by TNC/CXCL12 might be relevant for tethering CD8 TIL in the tumor stroma." (PMID 33988305, 2021). "In contrast, EPI-X4 as endogenous antagonist, being not useful as tumor-homing peptide, is highly efficient in suppressing signaling from CXCR4 and in inhibiting CXCL12-induced cancer cell migration in vitro and inflammatory cell infiltration in vivo." (PMID 34208189, 2021). "On the contrary, CXCL4, CXCL9, CXCL10, CXCL11, CXCL12, CXCL13, and CXCL14, lacking the ELR amino acid motif (ELR−), can inhibit tumor angiogenesis." (PMID 34497764, 2021). "CXCL12 excludes T cells from TME through a concentration gradient that inhibits immunoactive cells access and promotes tumor vascularization." (PMID 33937018, 2021). "Intratumoral CD8 + T-cell infiltration was significantly elevated in tumor tissues negative for PDGFRA and CXCL12 expression." (PMID 34801033, 2021). "In many types of cancer cells, chronic hypoxia does not increase the expression of CXCL12, although with an increased expression of CXCR4, the sensitivity of tumor cells to CXCL12 increases." (PMID 33467722, 2021). "In both groups, EG/CLG-inoculated, reduction of blood CXCL12 was observed at 72 h and 21 days post B16-hCXCR4-GFP cells inoculation suggesting that plasma CXCL12 was not influencing the propensity of tumor cell homing to the lungs/CLG." (PMID 31332163, 2019).
tumor (continued). "CXCL12 is expressed by microvascular endothelial cells and stimulated proliferation of GBM progenitor cells but not differentiated tumor cells via CXCR4, whereas ACKR3 was not involved." (PMID 30813533, 2019). "It is also compelling that CXCL12 and CXCR4 were both expressed more highly in the tumours of patients without angioinvasion or lymphatic invasion and vice versa." (PMID 29887884, 2018). "Although several studies have shown a strong connection between CXCL12/CXCR4 signalling towards MSCs migration and the tumour homing capacity, the knockdown of these receptors does not inhibit the homing potential of MSCs." (PMID 30060445, 2018). "In contrast to CXCL12 and TWIST1 methylation, the epigenetic regulation of the SNAI2 gene was previously determined only in BC cell line models, not in tumour samples." (PMID 30189837, 2018). "To figure out the role and significance of miR-137 and CXCL12 in the development of GBM, we firstly detected the expression of miR-137 and CXCL12 in 50 cases of tumor tissues and paired adjacent non-tumor tissues." (PMID 29254162, 2017). "Using Setup 2, we varied the number of CXCL12-secreting and -scavenging cells (non-endothelial CXCR7+ cells) in the tumor simulation." (PMID 29117251, 2017). "In the present study, immunohistochemical staining of CXCL12 and CXCR7 in two independent cohorts all discovered their higher expressions in tumor than non-tumor tissues." (PMID 27542220, 2016). "Therefore, aberrant expression of NF-κB induced by intrinsic or extrinsic factors may contribute to create a tumor microenvironment where a negative feedback loop inhibiting CXCR4/CXCL12 and VLA4/VCAM1 cellular communication axes allows for the maintenance of malignant cells." (PMID 27594840, 2016). "Which were derived from Beijing and Shanghai cohorts respectively, staining ranks of CXCL12 and CXCR7 in tumor tissues were statistically higher than those in non-tumor ones (P<0.001 and <0.001 for CXCL12; P=0.021 and =0.008 for CXCR7; Mann-Whitney U-test)." (PMID 27542220, 2016). "In our study, we also indicated that the concentrations of CXCL12 and CXCR4 were higher in patients with resectable tumors compared to those with nonresectable EC, similarly to classical tumor markers (data not shown)." (PMID 27041792, 2016). "Our study also found that effector B cells can kill tumor cells via cell-cell contact utilizing the Fas/FasL and CXCR4/CXCL12 pathways as well as perforin, while without cell contact, perforin secreted by B cells can also lead to tumor cell cytotoxicity." (PMID 27528023, 2016). "At the same tumour grade, there were no obvious differences in CCL5 and CXCL12 levels between the ESC and iPSC groups." (PMID 27417157, 2016). "Although the role of CXCL12/CXCR7 signaling is not yet fully described, this receptor seems to be essential for the survival and growth of tumor cells." (PMID 24629239, 2014). "CXCL12 expression was markedly absent, and CXCR4 and CXCR7 expression were more pronounced in human PDAC tumor cells." (PMID 24594697, 2014). "Although CXCL12 has been shown to bind to CXCR7, not much is currently known about the role of CXCL12/CXCR7 signaling in tumor growth and the early steps of metastasis within the primary tumors expressing CXCR7." (PMID 24886617, 2014). "On the other hand, the addition of CXCL12 or CCL18 ligand, not CCL4 ligand in the co-culture system of NFs and MDA-MB-231 enhanced transmigration of tumor cells by around 3-fold." (PMID 23577100, 2013). "Similar lack of CXCR7 down-regulation after CXCL12 treatment was observed in other cells which express endogenous CXCR7, such as monocytes, the monocytic cell line THP-1, B cell clones and tumor derived cells." (PMID 20161793, 2010). "This analysis showed down-regulated target gene (CXCL12, FABP1, MUC2 and PDCD4) expression in tumour compared to normal tissues, in keeping with their documented tumour suppressor functions, when using the larger set of samples." (PMID 20122155, 2010).
tumor (continued). "Taken together, we show high constitutive STAT3 phosphorylation in primary tumour samples from patients with SCLC but not from NSCLC, and constitutive and CXCL12-dependent activation of the JAK2/STAT3 pathway in SCLC cell lines." (PMID 19455144, 2009). "The other four genes (TNFAIP3/A20, COX2, CXCL12, and IER3L) were not expressed at significant levels (> 2 × background signal in at least 50% of all tumor samples)." (PMID 18248671, 2008). "Therefore, although the expression level of CXCL12, CXCR4 and CXCR7 has been considered a prognostic factor in several human tumor types, none of the actors of this axis have yet been definitively validated as pro-tumoral factors." (PMID 35406582, 2022). "However, using the endothelial cell line HUVEC, it was shown that this expression by vessels is not necessary for CXCL12-mediated transendothelial migration, and this process requires CXCR7 expressed by tumor cells, without involving CXCR4." (PMID 35406582, 2022). "The anti-CXCR4 antibody blocking of the CXCL12/CXCR4 axis was found to significantly reduce TEMs, but not Tie-2– TAMs, recruitment to combretastatin-A4-phosphate (the vascular-disrupting agent)-treated tumour in a murine model." (PMID 36497114, 2022). "Tumour cells expressing the receptor for CXCL12 (CXCR4), which is involved in metastasis, were strongly reduced, reflecting the effect of hypoxia on tumour cells, whereas CXCR4 expression was not affected in CD45+ cells or in the endothelial cell‐enriched population." (PMID 33624446, 2021). "Importantly, D-CAN treatment did not further suppress tumor growth in a-KO and b-KO mice, suggesting that D-CAN works at least in part through abrogating CXCL12 signaling via ASC ablation." (PMID 33753872, 2021). "Conversely, in MUC-1, RGZ did not modulate the CXCL12/CXCR4 axis, suggesting that the up-regulated CXCL12 in response to RGZ might be active only in the primary tumor but not in the metastatic cells." (PMID 34834449, 2021). "However, the relevance between CXCL12/CXCR4 and the differentiation of tumour cells towards Schwann‐like cell in PNI of SACC has not been investigated." (PMID 34170080, 2021). "Currently, the KEYNOTE 599 study is investigating the combination of a C-X-C motif chemokine 12 (CXCL12) inhibitor and pembrolizumab, intending to eliminate the negative immune regulatory effect of tumor microenvironment, which is highly enriched with CXCL12 (NCT03168139)." (PMID 35582227, 2020). "To test this hypothesis, we first ruled out the proliferation effects of CXCL12 on NET cell lines, since an accelerated proliferation could justify per se a more aggressive tumor behavior, thus promoting higher rates of skeleton colonization." (PMID 28186979, 2017). "Although CXCL12 promoted the proliferation index in vitro, and AMD3100 suppressed the proliferation index in vitro, as well as the tumor size in vivo, our study did not disclose whether the CXCL12/CXCR4 axis is responsible for ESCC survival or apoptosis." (PMID 27439769, 2016). "There was no relation between preoperative tumor size and CXCR4 or CXCL12 expression." (PMID 26920352, 2016). "CXCL12 secretion by stromal cells attracts cancer cells, acting through its cognate receptor CXCR4, which is expressed by both haematopoietic and non-haematopoietic tumour cells." (PMID 25598217, 2015). "Further interestingly, CXCL12, the ligand of CXCR4, is highly expressed in the surrounding pancreatic tissue of the PDAC tumor (data not shown) and may lure cells out of the tumor for invasion or further dissemination." (PMID 24069258, 2013). "In addition, we found significant differences between positive and negative CXCL12/CXCR4 samples in regards to the following clinicopathological features: i) lymph node metastasis and ii) tumor TNM staging." (PMID 23181100, 2012).